PKLR (pyruvate kinase L/R)
Diseases named in the same sentence as PKLR in open-access papers (continued):
Sharing a sentence is not in itself a finding about the gene and the disease.
anemia (3 papers, 2020 to 2024). A reduction in the number of red blood cells, the amount of hemoglobin, and/or the volume of packed red blood cells. "Application of WES as a new diagnostic approach in diagnosing rare types of anemia in Iran helped us to find the pathogenic mutations in the PKLR gene, including a novel variant in severe hemolytic anemia patients without diagnosis." (PMID 37542401, 2022). "Because of the serious defects of PKLR, our patients present with an extremely severe form of anemia requiring regular transfusions." (PMID 33193643, 2020).
diabetes (3 papers, 2008 to 2021). "Since it has been reported by a few research groups that PKLR affects the onset of diabetes, our study focused on the more specific role of pravastatin in regulating the protein expression of PKLR." (PMID 30926836, 2019). "Hence, we believe that pravastatin strongly interferes with the production of PKLR, which may ultimately result in the eventual onset of diabetes." (PMID 30926836, 2019). "Additionally, the PKLR and the NOS1AP genotypes were demonstrated not to have a major influence on diabetes-related quantitative metabolic phenotypes." (PMID 19111066, 2008).
leukemia (3 papers, 2017 to 2024). A malignant (clonal) hematologic disorder, involving hematopoietic stem cells and characterized by the presence of primitive or atypical myeloid or lymphoid cells in the bone marrow and the blood. "We identified the K562 leukemia cell line as having the highest PKLR expression using our recently published data in Cell Atlas and treated the cell line with C75, a FASN inhibitor, at different concentrations for 24 h." (PMID 28827398, 2017). "Most of the protein hits could be identified in blood samples according to the HPA database; two of them, namely DPEP1 and SOST, were classified by HPA as upregulated in BC; and five of them were found to be upregulated in leukemia and myeloma: SOST, TXNRD1, PKLR, EPHA2, PLIN3." (PMID 38791048, 2024).
colon cancer (2 papers, 2019). "However, recent study, have demonstrated that PKLR promotes colon cancer cell metastatic colonization of the liver by increasing glutathione synthesis, which is the primary endogenous antioxidant." (PMID 31692905, 2019). "PKLR promotes colon cancer cell metastases to the liver, but does not promote basal cell growth in culture." (PMID 30967137, 2019).
erythrocytosis (2 papers, 2020 to 2021). "A mild erythrocytosis has been reported also as a consequence of mutations in gene encoding cytochrome b5 reductase (B5R) enzyme, defects in PKLR gene, encoding glycolytic pyruvate kinase, and deficiency in the phosphofructokinase (PFK) enzyme." (PMID 34440324, 2021).
gastric cancer (2 papers, 2015 to 2024). A primary or metastatic malignant neoplasm involving the stomach. "Mutations in the PKLR gene are associated with overall cellular dysfunction due to disturbances in glycolytic metabolism and have been linked to gastric cancer, although their specific influence remains unclear." (PMID 39684297, 2024).
hereditary spherocytosis (2 papers, 2023 to 2024). Hereditary spherocytosis is a congenital hemolytic anemia with a wide clinical spectrum (from symptom-free carriers to severe hemolysis) characterized by anemia, variable jaundice, splenomegaly and cholelithiasis. "The frameshift p.Leu884GlyfsTer27 variant of ANK1, nonsense p.Trp652Ter variant of the SPTB, and missense p.Arg490Trp variant of PKLR were detected in all four hereditary spherocytosis cases." (PMID 36832257, 2023).
sickle cell disease (2 papers, 2024 to 2026). Sickle cell anemias are chronic hemolytic diseases that may induce three types of acute accidents: severe anemia, severe bacterial infections, and ischemic vasoocclusive accidents (VOA) caused by sickle-shaped red blood cells obstructing small blood vessels and capillaries. "Coinheritance of specific PKLR variants is associated with increased pain-related hospitalization and can trigger sickle cell disease (SCD) phenotypes in asymptomatic carriers." (PMID 41557517, 2026).
dementia (1 paper, 2023). Loss of intellectual abilities interfering with an individual's social and occupational functions. "Of these significantly positively correlated autoantibodies, five were differentially expressed in dementia and included CL1A, CBFA2T3, PKLR, APPL1, and NUDT2, whilst two were dysregulated in MCI including ABI1 and NUDT2." (PMID 38107644, 2023).
endometriosis (1 paper, 2023). The growth of functional endometrial tissue in anatomic sites outside the uterine body. "GCH1, RPL8, PKLR, and MAOA were the key targets of paeonol in the treatment of endometriosis." (PMID 36677710, 2023).
glioma (1 paper, 2017). A benign or malignant brain and spinal cord tumor that arises from glial cells (astrocytes, oligodendrocytes, ependymal cells). "The rate-limiting, irreversible and glycolysis-related enzymes hexokinase (HK2 and HK3) and pyruvate kinase (PKM2), but not HK1 or the pyruvate kinase isoform PKLR, were also expressed at lower levels in IDH1MUT glioma compared with IDH1WT glioma." (PMID 28467784, 2017).
hemochromatosis (1 paper, 2020). A disorder of iron metabolism characterized by a triad of HEMOSIDEROSIS; LIVER CIRRHOSIS; and DIABETES MELLITUS. "Of these five, two variants previously reported as pathogenic for autosomal recessive diseases (rs116100695 in PKLR for pyruvate kinase deficiency of red cells and rs1800730 in HFE for hemochromatosis) were found in apparently healthy homozygous UK Biobank participants." (PMID 32888494, 2020).
iron overload (1 paper, 2025). "An international study found that patients with NM/NM mutations exhibited more severe phenotypes, including higher rates of iron overload, transfusions, splenectomy, and lower post-splenectomy hemoglobin levels than those with missense/NM or missense/missense PKLR mutations." (PMID 41463922, 2025).
leprosy (1 paper, 2021). Leprosy is a chronic infectious disease affecting primarily the skin and peripheral nervous system. "Altogether, these findings suggest the association of PKLR SNPs with susceptibility to leprosy per se in Brazil, particularly in populations with high African ancestry, like Rio de Janeiro and Salvador, and with TB in Mozambique." (PMID 34449765, 2021). "In logistic regression, controlling for gender, age and ancestry and adjusting for FDR, the PKLR SNPs rs1052176, rs4971072 and rs11264359 were significantly associated with leprosy in Rio de Janeiro." (PMID 34449765, 2021). "A complete characterization of the biological effect of those risk variants may clarify the role of the PKLR gene in leprosy and tuberculosis." (PMID 34449765, 2021). "Altogether, we provide evidence that a common PKLR locus in Africans contribute to mycobacterial susceptibility in African descent populations and also highlight, for first, PKLR as a susceptibility gene for leprosy and TB." (PMID 34449765, 2021). "Although opposite OR were observed for the risk alleles in Rio de Janeiro due to differences in Asian genomic architecture, this result reinforces our hypothesis and underscores some relevance of the PKLR gene with susceptibility to leprosy." (PMID 34449765, 2021). "Moreover, variants under selection in the HCN3 are in LD with the SNP associated with leprosy susceptibility–rs1052176 –which is highlighted as an eQTL for PKLR and HCN3 genes by GTEx." (PMID 34449765, 2021). "As leprosy and TB are controlled by multiple variants (with “major” or “minor effect” in disease) and large-scale GWAS for disease traits predominantly identify common variants with weak effects (OR~1.2–1.7) shared across populations, the PKLR gene seems to contribute to this panel." (PMID 34449765, 2021). "Even though the association signal was not strong in Salvador or in Mozambique (the number of individuals might be a limiting factor), it was confirmed when combining the Brazilian sites, corroborating the role of PKLR gene with leprosy within Brazil." (PMID 34449765, 2021).
liver cancer (1 paper, 2021). An epithelial or non-epithelial malignant neoplasm that arises from the liver. "In contrast, we previously showed that PKLR was a possible liver-specific target for disease therapy, with PKLR inhibition potentially having more benefits and fewer complications for the treatment of liver cancer." (PMID 34512869, 2021).
Liver diseases (1 paper, 2017). "Liver diseases connected to FASN can thus be treated (by silencing PKLR, PCSK9 or PNPLA3) without experiencing the side effects associated with direct FASN inhibition." (PMID 28827398, 2017).
non-alcoholic fatty liver disease (1 paper, 2023). "We have previously established a computational pipeline for drug repurposing and identified JNK-IN-5A could modulate the expression of PKLR for effective treatment of non-alcoholic fatty liver disease." (PMID 37930015, 2023).
parasitemia (1 paper, 2022). "Continued work from the Gros laboratory described the existence of Char10, a region that controlled peak parasitemia and suppressed the effects of PKLR loss of function in a congenic line (AcB62)." (PMID 35646724, 2022).
prostate adenocarcinoma (1 paper, 2022). "We found that the AR-negative PC3 and NE-like NCI-H660 and LASCPC01 cell lines expressed higher PKLR and NE markers and lower androgen-responsive markers than did the AR-positive VCaP, LNCaP, and C4-2 prostate adenocarcinoma cell lines." (PMID 35306527, 2022).
prostate tumors (1 paper, 2022). "In studying the clinical relevance of PKLR, we found that prostate tumors from the Taylor PCa dataset with higher PKLR expression were associated with metastasis, and a high pathological grade based on the Gleason score (PathGGS)." (PMID 35306527, 2022). "The IHC analysis showed higher levels of PKLR in prostate tumors in patients who received ADT compared to the same patients before ADT; however, ZBTB10 levels were higher in patients before ADT and lower in patients after ADT." (PMID 35306527, 2022). "IHC results showed a reverse correlation between ZBTB10 and PKLR in consecutive tissue sections of prostate tumor samples." (PMID 35306527, 2022). "We studied key functions of PKLR in regulating glucose metabolism and NED progression in prostate tumors, by illuminating novel functions of PKLR in regulating NED-associated gene expressions." (PMID 35306527, 2022).
red blood cell disorders (1 paper, 2011). "We analyzed the variants in Glucose-6-phosphate dehydrogenase (G6PD) and isoforms of Pyruvate Kinase (PKLR & PKM2) genes responsible for major red blood cell disorders." (PMID 21931771, 2011).
sideroblastic anemia (1 paper, 2021). "The remaining new variants were identified in enzyme genes (PKLR: p.R531S; HK1: p.R12X, p.G451R; NT5C3A: p.R22X), and in genes associated with sitosterolemia (ABCG5: p.Y458X) and sideroblastic anemia (ALAS2: p.H524R)." (PMID 34093240, 2021).
Splenomegaly (1 paper, 2016). Abnormal increased size of the spleen. "P9, who has compound heterozygosity for two known pathogenic mutations in the PKLR gene, presented with neonatal liver failure and idiopathic inflammatory giant cell hepatitis and developed microcytic transfusion‐dependent anaemia with splenomegaly and reticulocytosis by 6 months of age." (PMID 27432187, 2016).
virus infection (1 paper, 2018). "In contrast, knockdown of PKLR expression reduced HCV and HBV replication, and supplementation with pyruvate rescued the inhibitory effects of the miR-130a mimic and PKLR gRNA on virus infection." (PMID 29321333, 2018). "Further understanding of the mechanisms by which miRNA, PKLR, and pyruvate regulate HCV and HBV replication through ATP and other glycolytic intermediates may facilitate the development of strategies to prevent establishment of persistent infection for HCV, HBV, and possibly other viral infections." (PMID 29321333, 2018).
tumor (24 papers, 2014 to 2025). "In this study, we investigated the role of PKLR in PCa and established the molecular basis of the tumor-promoting effects of PKLR that are associated with NEPC development after AR-targeted therapy." (PMID 35306527, 2022). "In particular, one gene, PKLR, was aberrantly methylated in HCC; PKLR encodes a pyruvate kinase and is involved in the glycolysis process and important for cancer metabolism and tumor growth." (PMID 25517360, 2014). "Like PFKM and GPD1, PKLR also has a variant with a VAF above 0.5, indicating a potential relationship with the initial stages of tumor formation and possible glycolytic dysfunction." (PMID 39684297, 2024). "We also showed that pharmacological inhibition of PKLR decreases tumor growth and NED progression in multiple in vitro and in vivo models of ADT-resistant and NE-like PCa cells, pointing to a potential approach for treating therapeutic-resistant PCa." (PMID 35306527, 2022). "We demonstrated that overexpression of ZBTB10 can suppress the glycolysis and oncogenic effects of PKLR, indicating the tumor-suppressive role of ZBTB10 in PCa." (PMID 35306527, 2022). "Together, our study is the first to reveal that circFOXP1 was upregulated in GBC and promoted the tumor progression in GBC cells by interacting with PTBP1 or sponging miR-370 targeting PKLR." (PMID 31623628, 2019). "PKLR provides cell survival in the central parts of a tumor, where the cells are in conditions of high density and hypoxia." (PMID 30967137, 2019). "enzyme pyruvate kinase, liver and RBC (PKLR) is identified as a pivotal regulator of glycolytic reprogramming and affect tumor cells." (PMID 31623628, 2019). "Mechanistic studies confirmed that circFOXP1 exerted its tumor-promoting roles by modulating the Warburg effect through upregulation of PKLR expression by interacting with PTBP1, protecting PKLR from mRNA decay." (PMID 31623628, 2019). "Pyruvate kinase L/R (PKLR) is a key enzyme in glycolysis that drives tumor development." (PMID 38773075, 2024). "To evaluate the potential tumor-suppressive effect of ZBTB10 in downregulating PKLR-driven PCa progression, we used a stable ZBTB10-expressing clone and compared it to ZBTB10-expressing cells rescued with the PKLR cDNA vector in AR-positive LNCaP and C4-2 cells." (PMID 35306527, 2022). "Additionally, circFOXP1 regulates the Warburg effect by interacting with PTBP1 to up-regulate the expression of PKR and exert its pro-tumor effect, eventually protecting PKLR from mRNA degradation." (PMID 34445958, 2021). "Contrastingly, PKLR might accelerate the progression of tumor cell growth but might also improve the survival of grafts after LT." (PMID 34512869, 2021). "BHLHE40 has been reported to have tumor suppressive functions and has been shown to affect energy metabolism by regulating PGC-1α, SREBP-1c, PKLR, PCK2, FASN, and PPARγ." (PMID 38301894, 2024). "Tumor tissues with high c-Met expression level in TCGA have increased expression of H6PD, PDK2, PDK4, PDPR, PKLR, SLC2A2 genes whereas decreased expression of GYS1, HK1, HK2, SLC2A1, significantly." (PMID 34059694, 2021). "CircFOXP1 interacted with PTBP1 or sponged miR-370, which promoted tumor progression and the Warburg effect in GBC by directly targeting the PKLR." (PMID 31623628, 2019). "A number of these genes (including PIK3R3, a member of the PI3K pathway, and PKLR, an isoform of pyruvate kinase) showed exceptionally strong co-expression with HNF4A in normal samples, only to have this co-expression abrogated in tumor samples." (PMID 25961905, 2015). "Due to PKLR’s role in promoting glycolysis through the conversion of phosphoenolpyruvate to pyruvate, depletion of FBP1 and the subsequent absence of PKLR in EVs impair nutrient availability and compromise the tumor surveillance function of NK cells." (PMID 38891772, 2024). "Neither KP−/−C;Pkm2+/+ nor KP−/−C;Pkm2flox/flox tumor lysates exhibited evidence for PKLR expression at the RNA or protein level." (PMID 30386596, 2018).
tumor (continued). "The data showed that the expression of only four out of 38 genes (HK3, FBP1, PKLR, GCK) was significantly affected by tumor purity (p < 0.01) but none of them was significantly differentially expressed between Gly and Non-Gly subtypes." (PMID 30873387, 2019).
cancer (12 papers, 2014 to 2025). A tumor composed of atypical neoplastic, often pleomorphic cells that invade other tissues. "PKLR appears to have a vital role in the Warburg effect, aerobic glycolysis which drives cellular proliferation, invasion and migration in cancers such as this." (PMID 33158116, 2020). "Glycolytic deregulation, including activation of upregulated PKM2 and liver and RBC (PKLR), is a driver that promotes cancer progression." (PMID 31623628, 2019). "Under these conditions, PKLR is required to maintain levels of the major endogenous antioxidant, a glutathione, and support cancer cell survival." (PMID 30967137, 2019). "By contrast, pyruvate kinase L/R (PKLR), an isozyme of PKM, had a high level of differential gene expression in both cancers." (PMID 34137202, 2021). "Next, we treated the HepG2 human cancer cell line with C75 and found that FASN expression and the expression levels of liver‐specific genes, including PKLR, PNPLA3, and PCSK9, were significantly decreased after 24 h." (PMID 28827398, 2017). "PKLR expression was absent in the mesenchymal SNU449 cells, which predominantly expressed PKM2, which is the more abundant form of PK in cancer cells, conferring substantial benefits on the rapidly growing tumorigenic cells." (PMID 28970582, 2017).
infection (5 papers, 2015 to 2023). The state of being infected such as from the introduction of a foreign agent such as serum, vaccine, antigenic substance or organism. "In these populations, we tested the hypothesis that coding or non-coding variants in the PKLR gene may be associated with differential response to the malarial parasite, including episodes and intensity of infections." (PMID 26658699, 2015). "Gene expression of pyruvate kinase L/R, PKLR, encoded the protein that is critical in glycolysis, was upregulated in the spike-infected NHBE cells at 72 h post infection (4.71-fold in Spike vs VSV-G, P = 0.0047)." (PMID 37504520, 2023). "We also observed a moderate reduction of PKLR mRNA expression after JFH1 infection." (PMID 29321333, 2018). "Thus, together with the slight differences in the hematological parameters, it is possible that the risk haplotype could affect iron protein levels and the expression of PKLR or adjacent genes in a way that favors the infection." (PMID 34449765, 2021). "PKLR overexpression or supplementation with pyruvate increased both HCV and HBV replication in several infection models." (PMID 29321333, 2018). "Furthermore, gene expression of glycolytic enzymes, lactate, and glutamine metabolism (G6PDH, PKLR, PFKL, LDHA, LDHB, GLS1, GLS2, and GLUL), were upregulated in primary mouse (hACE2) and human hepatocytes upon infection compared to controls." (PMID 35978143, 2022).
adenocarcinoma (1 paper, 2022). A common cancer characterized by the presence of malignant glandular cells. "Importantly, levels of PKLR were higher in PCa patients with NEPC compared to patients with adenocarcinomas in Aggarwal datasets." (PMID 35306527, 2022).
PKLR also shares sentences with these, for which no sentence is quoted: metabolic disease (4 papers); melanoma (2); autosomal recessive disease (1); chronic gastritis (1); colorectal cancer (1); Crigler-Najjar syndrome type 2 (1); esophageal carcinoma (1); esophageal squamous cell carcinoma (1); G6PD deficiency (1); hemoglobinopathies (1); hemophilia B (1); hereditary nonspherocytic hemolytic anemia (1); Insulin resistance (1); lung adenocarcinoma (1); lung carcinoma (1); macrocytic anemia (1); metastatic cancer (1); myeloma (1); myeloperoxidase deficiency (1); neutropenia (1); non-spherocytic hemolytic anemia (1); Obesity (1); phospholipidosis (1); prostate carcinoma (1); pulmonary hypertension (1); red cell pyruvate kinase deficiency (1); sensitive (1); Sepsis (1); sitosterolemia (1); thalassemia (1).
A further 2 diseases each share a sentence with PKLR in 1 paper.